MTA3 (metastasis associated 1 family member 3)
Diseases named in the same sentence as MTA3 in open-access papers (continued):
Sharing a sentence is not in itself a finding about the gene and the disease.
cancer (26 papers, 2009 to 2025). A tumor composed of atypical neoplastic, often pleomorphic cells that invade other tissues. "Loss of MTA3 expression is frequently observed in advanced-stage cancers and is accompanied by reduced E-cadherin expression and aberrant β-catenin localization." (PMID 41584603, 2025). "Epigenome-wide analysis identified three CpGs with suggestive p-values ≤10− 5 for differential methylation between cancer-free and cancer-present groups, including a CpG located in MTA3, a gene linked with metastasis." (PMID 31149338, 2019). "MTA3 expression was reported to be associated with differentiation, cancer progression, and overall survival rates." (PMID 28279208, 2017). "MTA3 dysregulation is associated with tumor progression, invasion, and metastasis in various cancers." (PMID 28279208, 2017). "All family members of metastasis tumor antigen (MTA) proteins including MTA1, MTA2, MTA3 and MTA1s have been closely linked to cancer progression and metastasis." (PMID 23671646, 2013). "Thus, we have identified two types of transcripts: (a) transcripts that are not expressed in normal conditions and are gained in cancer (e.g. CIT, CCNE1) and (b) transcripts that gain an additional cancer-associated transcript (e.g. MTA3, ZFHX3)." (PMID 33499898, 2021). "MTA3 is a chromatin remodeling protein that has a complex association with cancer." (PMID 31149338, 2019). "Metastasis-associated protein 3 (MTA3), a component of the nucleosome remodeling and histone deacetylase (NuRD) complex and multi-effect coregulator, can serve as a tumor suppressor in many cancer types." (PMID 31552166, 2019). "Subsequent studies revealed a more intricate role for MTA3 in tumorigenesis, revealing context-dependent dual functionality—either promoting or inhibiting cancer progression—depending on tumor type, disease stage, and the microenvironment." (PMID 41584603, 2025). "HCC is a prevalent and invasive malignant tumor, and its progression is driven by complex molecular networks in which MTA3 has emerged as a key player." (PMID 41584603, 2025). "Functional studies have demonstrated that, unlike MTA1 and MTA2, which predominantly facilitate tumor progression, MTA3 was initially reported to suppress cancer cell invasion and metastasis." (PMID 41584603, 2025). "The upregulation of the FOXA1 transcription factor network and the downregulation of the MTA3 pathway point to significant transcriptional reprogramming, consistent with reports that the MTA3 protein is often upregulated in cancers." (PMID 40002253, 2025). "MTA1 expression was positively correlated with cancer histological grade, whereas those of MTA3 and TRIM21 were the opposite." (PMID 39154024, 2024). "MTA3 exerts transcriptional repression mainly through the NuRD complex to suppress cancer cell stemness and metastasis and ultimately inhibit tumorigenesis." (PMID 39154024, 2024). "As a transcription factor, MTA3 becomes a cancer suppressor by inhibiting the proliferation, invasion, and migration of cancer cells." (PMID 32973538, 2020). "Data from gene set enrichment analysis (GSEA) also indicated that MTA3 was inversely correlated with cancer stemness." (PMID 31552166, 2019). "Consistently, the dysfunctional MTA3 reduces cell-cell adhesion and promotes cancer invasion and metastasis." (PMID 31552166, 2019). "Compelling evidence suggests that MTA3 is a tumor suppressor in many cancer types by serving as an integral subunit of the nucleosome remodeling and histone deacetylase (NuRD) complex." (PMID 31552166, 2019). "We also showed that MTA3 was capable of repressing cancer cell proliferation through inhibiting SOX2 expression." (PMID 31552166, 2019). "In this study, we found that reduced levels of MTA3 in the patient specimens correlated with poorer clinical outcomes with concurrently increased cancer stemness." (PMID 31552166, 2019).
cancer (continued). "This is indicative of an inverse relation between MTA3 and SOX2 associated with cancer occurrence and development, which was confirmed in mouse TSCC by double immunofluorescent staining." (PMID 31552166, 2019). "It is well known that MTA3 is involved in cancer cell migration by regulating cell adhesion proteins." (PMID 28279208, 2017). "Although MTA3 is involved in multiple cellular activities in physiological and pathologic processes, MTA3 has been extensively studied for its regulation and association with EMT and metastasis in cancer." (PMID 28279208, 2017). "MTA3 protein is required in normal development for sustaining the controlled cell growth and homeostasis and, in cancers, to combat the spread of cancers through EMT and metastasis." (PMID 28279208, 2017). "MTA3 has been recognized as a master inhibitor of EMT in cancer, which inhibits Snail to increase E-cadherin expression." (PMID 23671646, 2013). "Considering the many reports showing the clinical relevance of the expression of MTA3, it is likely that MTA3 represents master co-regulatory molecules involved in the carcinogenesis and progression of various malignant tumors." (PMID 24107548, 2013). "In support of above findings, we analyzed MTA3 mRNA level in the human cancer microarray database Oncomine." (PMID 23671646, 2013). "Furthermore, therapeutic agents, including the histone deacetylase inhibitor LBH589 and the natural compound β-elemene, modulate cancer cell migration and invasion by regulating the MTA3–Snail–E-cadherin axis." (PMID 41584603, 2025). "Furthermore, the MTA3 expression levels were correlated with cancer hallmarks, including the G2/M checkpoint, E2F1 targets, and MYC targets." (PMID 36050478, 2022). "MTA3 belongs to the family of metastasis associated proteins, known for their role in cancer progression; however, there are no studies describing its role in gametes or embryonic development." (PMID 32640983, 2020). "However, unlike MTA1 and MTA2 which were mainly involved in cancer progression and metastasis, MTA3 possesses both tumor-suppressing and tumor-promoting properties depending on specific cancer types." (PMID 31552166, 2019). "Moreover, we established the negative regulation of SOX2, a key regulator in the plasticity of cancer stemness, by MTA3 repressed the number of ALDH1-positive cells and cell proliferation in TSCC cells." (PMID 31552166, 2019). "MTA3 was first found to be down-regulated in cancers and repress EMT and invasion." (PMID 28279208, 2017). "In hormone-independent types of cancer, MTA3 was also found to could suppress tumor cell invasion and metastasis by inhibiting Wnt-target genes through directly targeting the transcription of Wnt." (PMID 28418887, 2017). "From a translational viewpoint, the association between MTA3-mediated signaling, aggressiveness, and clinical outcomes has not been fully examined in different cancers." (PMID 28279208, 2017). "A decrease of MTA3 expression leads to the up-regulation of Snail and triggers the process of EMT by repressing E-cadherin, thereby causing a loss of cell-to-cell adhesion and promoting cancer invasion and metastasis." (PMID 28279208, 2017). "In contrast to MTA1 and MTA2, which are usually upregulated in cancer, MTA3 is downregulated." (PMID 23671646, 2013). "To date, studies on MTA3 have only limited to a few types of cancers." (PMID 23671646, 2013). "Reports of MTA3 in human cancers were quite limited initially." (PMID 23840517, 2013). "Besides down-regulation, MTA3 was also found to be up-regulated in cancers." (PMID 28279208, 2017). "Compared with MTA1 and MTA2, MTA3 may have more complex functions in cancer progression." (PMID 28279208, 2017). "It has been reported that MTA3 could inhibit the transcription of Snail gene and alter downstream gene expression including E-Cadherin, by which MTA3 may take part in the regulation of cancer cell invasion, metastasis and mediate epithelial to mesenchymal transition (EMT)." (PMID 28418887, 2017).
cancer (continued). "Decreased levels of MTA3 result in upregulation of Snail, an event that has been identified as a trigger of EMT by causing repression of the E-cadherin cell adhesion molecule, thereby leading to a loss of cell-cell adhesion and contributing to cancer invasion and metastasis." (PMID 23671646, 2013). "MTA3 negatively regulates SOX2, a key transcription factor involved in cancer stem cell maintenance, thereby suppressing the stem-like properties and proliferative capacity of tumor cells." (PMID 41584603, 2025). "Previous studies have indicated that MTA1 and MTA2 support tumor progression and EMT, while MTA3 inhibits EMT and cancer metastasis." (PMID 36575438, 2022). "miR-766-3p is also known as a dual player in cancer, it showed an anti-cancer effect on HCC by targeting WNT3A, but it is also known to inhibit cell-cycle progression and metastasis of RCC by targeting SF2 and HCC by targeting MTA3, respectively." (PMID 33435549, 2021). "In addition, the levels of MTA3 in both samples from TSCC patients and TSCC cell lines were negatively correlated with SOX2, a key regulator of the plasticity of cancer stem cells (CSCs)." (PMID 31552166, 2019). "In summary, MTA3 is a decisive modulator for EMT and metastasis in cancers." (PMID 28279208, 2017). "MTA3 overexpression serves as a prognostic marker for judging the survival of uterine non-endometriod cancer patients." (PMID 23840517, 2013). "Considering the key regulatory function of MTA3 in cancer and other human diseases, as well as the lack of comprehensive reviews summarizing its mechanistic actions and clinical translational potential, this article is dedicated to MTA3." (PMID 41584603, 2025).
tumor (20 papers, 2009 to 2025). "Contrarily, among individuals of Zhuang ethnicity, elevated MTA3 expression was significantly associated with advanced age, tumor recurrence, and metastasis, as well as independently predicted adverse outcomes." (PMID 41584603, 2025). "Evidence indicates that MTA3 expression is significantly upregulated in HCC tissues compared to adjacent non-tumor tissues, and its overexpression is strongly associated with reduced overall survival." (PMID 41584603, 2025). "MTA3 regulates gene expression through epigenetic mechanisms and is implicated in both neoplastic and non-neoplastic diseases." (PMID 41584603, 2025). "Numerous clinical studies have reported frequent overexpression of MTA3 in tumor tissues, which is significantly associated with advanced p-TNM stage, lymph node metastasis, and poor prognosis." (PMID 41584603, 2025). "Further mechanistic investigations have revealed that dysregulation of the MTA3/Snail/E-cadherin axis is closely associated with tumor differentiation status, lymph node metastasis, and advanced TNM staging." (PMID 41584603, 2025). "In the present study, we investigated the protein expression of MTA3 by immunohistochemistry assay, analyzed its association with tumor progression, recurrence and prognosis in239 cases of patients." (PMID 28418887, 2017). "In summary, our results demonstrate that misexpression of MTA3-pathway components is closely associated with parameters involving invasion/metastasis, and tumor advancement." (PMID 23671646, 2013). "Moreover, MTA3 participates in regulating Tfh cell-associated gene expression programs, thereby modulating the tumor immune microenvironment." (PMID 41584603, 2025). "While we could not replicate this CpG in the Roos dataset, the collective evidence suggests that methylation changes in the CpG island of MTA3 may be associated with tumor development and progression." (PMID 31149338, 2019). "As invasion and metastasis could determine tumor recurrence and corresponding outcome, we next analyzed the association of MTA3 level with disease-free and overall survival." (PMID 28418887, 2017). "Nevertheless, other independent factors with a potential influence on survival that have recently been discussed could be considered, e.g. an overexpression of MTA3 gene in NSCLC as a risk factor on survival or an overexpression of IMP3 as a predictor of aggressive tumor behavior." (PMID 24593867, 2014). "Mechanistically, the long non-coding RNA HCG11 acts as a molecular sponge for miR-4425, thereby relieving miR-4425-mediated repression of MTA3 and subsequently inhibiting tumor growth." (PMID 41584603, 2025). "Recent studies have revealed that MTA3 functions not only as an independent prognostic biomarker in HCC but also as a key oncogenic factor involved in tumor progression and immune modulation, highlighting its significant potential for clinical translation." (PMID 41584603, 2025). "The hypomethylated epigenetic signal was enriched for a number of transcription factor binding sites, including MTA2 and MTA3 which have been shown to have relationships to metastasis and tumor growth in multiple cancers." (PMID 41000815, 2025). "Accumulating evidence indicates that MTA3 expression is significantly downregulated in TSCC, and its reduced levels are significantly associated with tumor progression and poor prognosis." (PMID 41584603, 2025). "Conversely, exogenous overexpression of MTA3 effectively reversed the miR-367-induced malignant phenotype, indicating that MTA3 inhibits tumor progression in ccRCC." (PMID 41584603, 2025). "In animal models, colchicine suppresses MTA3 expression and increases tumor cell sensitivity to GEM." (PMID 41584603, 2025). "In non-neoplastic diseases, MTA3 exerts regulatory effects by modulating inflammatory and fibrotic processes." (PMID 41584603, 2025). "MTA3 is frequently overexpressed in the nuclei of HCC cells and is significantly associated with tumor metastasis and adverse patient prognosis." (PMID 41584603, 2025).
tumor (continued). "Our qChIP results showed that MTA1 transcriptionally regulates tumor suppressors, including MTA3 and TRIM21." (PMID 39154024, 2024). "The Tumor Immune Estimation Resource (TIMER2.0) was used to estimate the relevance of MTA3 to immune cell infiltration." (PMID 38852126, 2024). "A mechanistic analysis revealed that MTA3 functions as the downstream target of SPHK1 in transcriptionally regulating tumor PD-L1." (PMID 36050478, 2022). "Preclinically, we found that anti-PD-1 monoclonal antibody (mAb) treatment significantly rescued tumor SPHK1 overexpression or tumor MTA3 overexpression-mediated immune evasion." (PMID 36050478, 2022). "Intriguingly, we observed that SPHK1- or MTA3-induced tumor proliferation was substantially suppressed by anti-PD-1 mAb treatment, as demonstrated by a reduction in the tumor growth rate." (PMID 36050478, 2022). "Univariate analyses found that MTA3 expression, pTNM stage, pN status, and tumor depth were significantly related to TSCC patient outcome." (PMID 31552166, 2019). "It is found that MTA3 expression level is significantly increased in hepatocellular carcinoma and identified to correlate with tumor progression and the poor prognosis." (PMID 28968973, 2017). "In this study, we discovered that expression of MTA3-pathway components was altered in tumor tissues, and the altered expression was strongly correlated with metastasis and tumor advancement." (PMID 23671646, 2013). "To date, studies on MTA3 expression have been limited to a few hormone-responsive malignancies, such as tumors of the breast, ovary, endometrium, and placenta." (PMID 23671646, 2013). "MTA3 protein expression was observed in the nuclear compartments of tumor cells, while the normal bronchial epithelia exhibited negative or low staining." (PMID 23840517, 2013). "Expression of Duox was studied by immunohistochemistry on a multi-tumor tissue microarray (TARP MTA3) containing 217 analyzable tumor samples and a sampling of normal tissue." (PMID 23404210, 2013). "The effect of up-regulation of MTA3 on the tumour cell line is even less clear: as it is known that the fate determination of H929 cells is dependent on MTA3, perhaps MTA3 is playing a pivotal role in fate determination of the transformed BRK cells." (PMID 19200380, 2009). "The overexpression of MTA3 is hypothesized to modulate the expression of immune-related molecules on the tumor cell surface, thereby impacting immune cell recognition and cytotoxic activity." (PMID 41584603, 2025). "The MTA3-related signaling pathway was significantly enriched in tumor samples." (PMID 41584603, 2025). "Furthermore, the role of MTA3 within the tumor microenvironment and its involvement in immune regulation should be investigated to establish a foundational theoretical basis for its potential as a target in combination therapies." (PMID 41584603, 2025). "The role of MTA3 in regulating tumor invasion has attracted growing research interest." (PMID 41584603, 2025). "However, the relationship between MTA3 and PD-L1 and the role of MTA3 in the tumor microenvironment are much less clear." (PMID 36050478, 2022). "However, activity in these types of networks was not restricted to cluster LCH_0, as e.g. in cluster LCH_1 higher regulon activity was seen in MTA3, which functions both as an oncogene and as a tumor suppressor." (PMID 36525505, 2022). "Similarly, the presence of MTA1 in NuRD complexes correlates with metastatic growth of human tumor tissue and MTA3 with normal growth and differentiation." (PMID 29490265, 2018). "Additionally, MTA3 might influence cytokine secretion, contributing to the establishment of an immunosuppressive microenvironment that impedes the infiltration and activation of immune cells, consequently attenuating the anti-tumor immune response." (PMID 41584603, 2025).